TOM1 (target of myb1 membrane trafficking protein)
Description:
Adapter protein that plays a role in the intracellular membrane trafficking of ubiquitinated proteins, thereby participating in autophagy, ubiquitination-dependent signaling and receptor recycling pathways. Acts as a MYO6/Myosin VI adapter protein that targets MYO6 to endocytic structures. Together with MYO6, required for autophagosomal delivery of endocytic cargo, the maturation of autophagosomes and their fusion with lysosomes. MYO6 links TOM1 with autophagy receptors, such as TAX1BP1; CALCOCO2/NDP52 and OPTN. Binds to polyubiquitinated proteins via its GAT domain. In a complex with TOLLIP, recruits ubiquitin-conjugated proteins onto early endosomes. The Tom1-Tollip complex may regulate endosomal trafficking by linking polyubiquitinated proteins to clathrin. Mediates clathrin recruitment to early endosomes by ZFYVE16. Modulates binding of TOLLIP to phosphatidylinositol 3-phosphate (PtdIns(3)P) via binding competition; the association with TOLLIP may favor the release of TOLLIP from endosomal membranes, allowing TOLLIP to commit to cargo trafficking. Acts as a phosphatidylinositol 5-phosphate (PtdIns(5)P) effector by binding to PtdIns(5)P, thereby regulating endosomal maturation. PtdIns(5)P-dependent recruitment to signaling endosomes may block endosomal maturation. Also inhibits Toll-like receptor (TLR) signaling and participates in immune receptor recycling.
Synonyms: IMD85
Tractability: Antibody: UniProt places it where antibodies can reach, with high confidence; its Gene Ontology location is reachable by antibodies, with high confidence. PROTAC: UniProt records ubiquitination sites on it; ubiquitination databases record sites on it; its protein half-life has been measured.
Gene: Protein-coding gene on chromosome 22 (35,299,275 to 35,347,995, forward strand). Ensembl gene ENSG00000100284.
Subcellular location: Cytoplasm; Endosome membrane; Early endosome membrane
Subcellular location (Human Protein Atlas): Cytosol; Golgi apparatus
Pathways (Reactome):
Immune System: Neutrophil degranulation
Gene Ontology:
Molecular function: clathrin binding; clathrin heavy chain binding; myosin VI binding; phosphatidylinositol-5-phosphate binding; polyubiquitin modification-dependent protein binding; protein binding; ubiquitin binding; phosphatidylinositol binding
Biological process: autophagosome-lysosome fusion; endosomal transport; positive regulation of autophagosome maturation; regulation of endosome organization; substrate localization to autophagosome; endocytosis; protein transport; signal transduction
Cellular component: cytoplasm; cytosol; early endosome; early endosome membrane; endosome; endosome membrane; extracellular exosome; membrane; azurophil granule membrane; plasma membrane; specific granule membrane
Genetic constraint (gnomAD): Loss-of-function variants: 40 observed, 60.12 expected, observed/expected ratio (o/e) 0.67, 90% interval 0.52 to 0.87. The upper end of that interval is the gene's LOEUF score, 0.87, which puts it in group 3 of 6, group 1 being the genes least tolerant of losing a copy. Missense variants: 591 observed, 664.12 expected, observed/expected ratio (o/e) 0.89, 90% interval 0.83 to 0.95. Synonymous variants: 270 observed, 272.05 expected, observed/expected ratio (o/e) 0.99, 90% interval 0.9 to 1.1.
Homologues: Orthologues: chimpanzee TOM1 (99% identical), macaque TOM1 (96% identical), pig TOM1 (93% identical), mouse Tom1 (89% identical), rat Tom1 (89% identical), rabbit TOM1 (89% identical), guinea pig TOM1 (85% identical), dog TOM1 (83% identical), tropical clawed frog tom1 (69% identical), zebrafish tom1 (43% identical), Drosophila melanogaster CG3529 (41% identical), Caenorhabditis elegans C07A12.7 (36% identical), and 5 more. Paralogues in human: TOM1L2 (63% identical), TOM1L1 (32% identical), GGA3 (26% identical), GGA1 (25% identical), HGS (22% identical), STAM (21% identical), GGA2 (21% identical), STAM2 (20% identical), WDFY1 (11% identical), WDFY2 (11% identical).
Diseases named in the same sentence as TOM1 in open-access papers:
TOM1 is named in the same sentence as 28 diseases in open-access papers, as found by Europe PMC text mining. Sharing a sentence is not in itself a finding about the gene and the disease. The quoted sentences say what the papers report.
Autoimmunity (3 papers, 2019 to 2025). The occurrence of an immune reaction against the organism's own cells or tissues. "The G307D variant of TOM1, an endosomal adaptor protein, has been linked to inborn errors of immunity – conditions that manifest as increased susceptibility to infections, autoimmunity, autoinflammation, severe allergy and malignancy." (PMID 41111332, 2025). "A recently described G307D variant of the endosomal adaptor protein TOM1 causes severe early-onset multiorgan autoimmunity and combined immunodeficiency." (PMID 40936361, 2025). "We report here a heterozygous TOM1 p.G307D missense mutation, detected by whole-exome sequencing, in two related patients presenting with early-onset autoimmunity, antibody deficiency, and features of combined immunodeficiency." (PMID 31263572, 2019). "In sum, we report here an identification of a novel gene, TOM1, associating with early-onset autoimmunity, antibody deficiency, and features of combined immunodeficiency." (PMID 31263572, 2019).
cystic fibrosis (2 papers, 2014 to 2021). Autosomal recessive disorder caused by pathogenic variants in the CFTR gene (cystic fibrosis transmembrane conductance regulator), which encodes a chloride and bicarbonate channel expressed in epithelial cells, and follow the diagnosis criteria. "TOM1 is also involved in the Toll-like receptors 2/4 (TLR2/4) signaling pathways in cystic fibrosis, an inherited disorder characterized by chronic airway inflammation." (PMID 33718385, 2021). "miR-126 controls TLR2/4 inflammatory signaling pathways by modulating TOM1 expression in cystic fibrosis lung." (PMID 25070658, 2014). "Thus, in addition to the regulation of IL-1R1 surface expression, the TOM1-TOLLIP complex may also modulate TLR2/4 recycling by employing a similar mechanism, thereby having an anti-inflammatory role in cystic fibrosis and possibly in other inflammatory diseases." (PMID 33718385, 2021).
multiple myeloma (2 papers, 2004 to 2022). "By contrast, most cell lines of B-cell lineage, including multiple myeloma, show no CIITA-PIV methylation; two (TOM1 and RPMI8226) showed slight methylation." (PMID 14970863, 2004).
-CoV-2 infection (1 paper, 2026). "Importantly, TOM1 overexpression suppresses SARS-CoV-2 replication in HEK293T-hACE2 and Vero cells, while TOM1 knockout via CRISPR-Cas9 significantly enhances viral propagation, indicating that TOM1 functions as a novel restriction factor against SARS-CoV-2 infection." (PMID 42283626, 2026).
cervical cancer (1 paper, 2023). A primary or metastatic malignant neoplasm involving the cervix. "The intersection of LASSO and SVM-RFE analyses revealed eight hub genes in cervical cancer, which were RBBP4, SRM, GCH1, USP14, TRAIP, CBX4, VEZF1, and TOM1." (PMID 36999051, 2023).
deafness (1 paper, 2016). An inherited or acquired condition characterized by the complete loss of the ability to hear from one or both ears. "An myosin VI mutation (3496C > T) that causes deafness in Pakistani families leads to a premature stop in the C-terminal cargo-binding tail domain (at R1166X) and loss of the WWY motif, the binding site for myosin VI adaptor proteins, including Dab2, LMTK2 and Tom1/L2." (PMID 27474411, 2016).
lung tumors (1 paper, 2018). "However, expression levels of downstream markers TPM-1, TOM-1, CRK, fibulin-2, MIF, and EFNA-3 were greater in the lung tumors than in non-tumor specimens only in patients without COPD." (PMID 29371906, 2018).
malaria (1 paper, 2012). Malaria is a serious and sometimes fatal disease caused by a parasite that commonly infects a certain type of mosquito which feeds on humans. "Moreover, the two genes immediately flanking the HMOX1 gene (TOM1 33 kb 5′ and MCM5 6 kb 3′ of HMOX1) are not obvious candidates for malaria susceptibility." (PMID 22438807, 2012).
memory impairment (1 paper, 2021). "The authors also found that memory impairment in TOM1-expression deficient mice was rescued by replenishing the TOM1 gene, supporting the role of TOM1 in AD-associated memory deficits." (PMID 33718385, 2021).
myocardial infarction (1 paper, 2024). Gross necrosis of the myocardium, as a result of interruption of the blood supply to the area, as in coronary thrombosis. "The involvement of genes such as AGPS, MYO9B, PYGB, TOM1, UBA52, and UBB in myocardial infarction is first reported in this study." (PMID 39872885, 2024).
sarcoma (1 paper, 2025). A usually aggressive malignant neoplasm of the soft tissue or bone. "TOM1, identified in the sarcoma group, is also a gene involved in the autophagy process, and it has been revealed that a low level of TOM1 is associated with an increased incidence of solid tumors." (PMID 40446009, 2025).
infection (6 papers, 2007 to 2024). The state of being infected such as from the introduction of a foreign agent such as serum, vaccine, antigenic substance or organism. "Infection of eukaryotic cells by Shigella flexneri boosts oxygen consumption and promotes the synthesis of phosphatidylinositol-5-phosphate (PtdIns5P), which triggers Tom1 translocation to signaling endosomes." (PMID 31350523, 2019). "TOM1 interacts with the helicase domain of TMV replicase to form the replication complex, and supports tobamovirus multiplication on an early stage of infection with TOM3." (PMID 28702034, 2017). "A previous study demonstrated that in A. thaliana, tobamoviruses require both TOM1 and TOM2A to build a replication complex during the early stages of infection; however, in later stages of infection, the replication complex is also formed without TOM2A." (PMID 38262958, 2024).
cancer (5 papers, 2021 to 2025). A tumor composed of atypical neoplastic, often pleomorphic cells that invade other tissues. "More importantly, dysfunction of the Huwe1 (a homolog of yeast Tom1) has been linked with multiple types of cancer and intellectual impairment, and Huwe1 has become a novel therapeutic target for the treatment of cancer." (PMID 37504517, 2023). "First, in terms of immune function, variations related to the nuclear factor kappa B (NF-κB) signaling pathway (NLRP12, TNIP2, IRAK4) and the autophagy process (TECPR1, ATG2A, SOGA1, TOM1) were identified in both carcinoma and sarcoma tumor groups." (PMID 40446009, 2025). "Alteration of TOM1 function has emerged as a phosphoinositide-dependent survival mechanism for bacterial infections and cancer progression." (PMID 33718385, 2021). "The cluster for GC versus GIN was mostly related to energy metabolism, cancer metastasis, and invasions, such as LAMTOR1 and TOM1." (PMID 35958927, 2022). "Furthermore, 50 signaling pathways were analyzed, among which TOM1 and UBA3 were more important for cancer proliferation, invasion and metastasis." (PMID 38298057, 2024).
tumor (4 papers, 2018 to 2025). "The second module (M2) was composed of multiple metabolism-relevant phosphoproteins like PGK1, PSMF1, PRDX1, and TOM1, they showed lower expressions in the tumor tissues, especially the high RR tumor tissues." (PMID 38609408, 2024). "Tumor expression levels of miR-126 did not significantly differ between LC-COPD and LC patients, whereas in the former patients, an almost significant decrease in EGFL-7 expression was observed (p = 0.073), together with a decrease in TOM-1 and CRK expression and a rise in angiopoietin-2 content." (PMID 29371906, 2018).
bacterial infection (2 papers, 2019 to 2021). "Results are discussed within the context of Tom1 recruitment to PtdIns5P-enriched endosomal compartments under bacterial infection conditions." (PMID 31350523, 2019). "Thus, conformation of the PtdIns5P-bound Tom1 VHS, found at a physiological temperature, may have a role in the progress of bacterial infection by facilitating yet-to-be-determined molecular interactions." (PMID 31350523, 2019). "In addition, the PtdIns5P-dependent conformational change of the VHS domain may explain why Tom1 is no longer engaged in ubiquitinated protein trafficking under bacterial infections." (PMID 31350523, 2019).
TOM1 also shares sentences with these, for which no sentence is quoted: Immunodeficiency (2 papers); antibody deficiency (1); autoimmune disease (1); glioma (1); heart failure (1); human papillomavirus infection (1); legionellosis (1); leishmaniasis (1); neurodevelopmental disorder (1); Stroke (1); ulcerative colitis (1); viral infection (1); X-linked intellectual disability (1).